SIRT7 (sirtuin 7)
Diseases named in the same sentence as SIRT7 in open-access papers (continued):
Sharing a sentence is not in itself a finding about the gene and the disease.
fatty liver disease (13 papers, 2016 to 2025). A reversible condition wherein large vacuoles of triglyceride fat accumulate in liver cells via the process of steatosis. "In contrast, other studies have paradoxically reported that loss of SIRT7 can instead protect against high-fat-diet-induced hepatic steatosis by stabilizing TR4/TAK1, a nuclear receptor involved in lipid metabolism and fatty acid uptake." (PMID 41471367, 2025). "Sirt7-deficient mice (which have exons 4–11 replaced with the LacZ gene) experience chronic hepatosteatosis like human fatty liver disease." (PMID 37676263, 2024). "Selectively overexpression of SIRT7 in the liver of Sirt7-KO mice via adeno-associated virus 8 (AAV8)-mediated gene transfer prevents the development of fatty liver." (PMID 30574122, 2018). "On one side, SIRT7 deficiency was reported to prevent hepatic steatosis by a high-fat diet." (PMID 35585284, 2022). "SIRT7 functions at chromatin to suppress ER stress and prevents fatty liver disease, and SIRT7-deficient mice develop chronic hepatosteatosis resembling human fatty liver disease, and liver-specific reconstitution of SIRT7-deficient mice reversed the fatty liver phenotype." (PMID 34129782, 2021). "In the context of lipid metabolism, SIRT7‐knockout mice developed chronic hepatic steatosis as they accumulated greater quantities of triglycerides than wild‐type mice and this phenotype was reverted by SIRT7 restoration in the liver." (PMID 39215785, 2025). "Mechanistically, SIRT7 interacts with the Myc transcription factor to silence ribosomal protein transcription and alleviate endoplasmic reticulum (ER) stress to reverse fatty liver disease." (PMID 37676263, 2024). "In contrast to SIRT1 and SIRT6, SIRT7 functions as a positive regulator of hepatic lipid accumulation, and Sirt7 KO mice are resistant to HFD-induced fatty liver." (PMID 38201252, 2023). "At the mechanistic level, it seems that SIRT7 prevents the development of fatty liver disease by suppressing ER stress." (PMID 30510540, 2018). "Systemic suppression of SIRT7 could recapitulate phenotypes observed in knockout animal models, including metabolic dysfunctions (e.g., hepatic steatosis), osteopenia, inflammatory disorders, cardiomyopathy, and other abnormalities." (PMID 41471367, 2025). "SIRT7 (KO) mice are resistant to high-fat-diet-induced fatty liver disease and glucose intolerance." (PMID 32404984, 2020). "Evidence suggests that SIRT7 suppresses endoplasmic reticulum stress (ER stress) via acting as a cofactor of Myc for transcription repression to modulate ER stress; SIRT7 knock out mice show chronic hepatosteatosis resembling fatty liver disease in humans." (PMID 30216989, 2018). "Importantly, liver steatosis was reversed in these animals by reintroducing SIRT7 specifically in the liver." (PMID 30510540, 2018). "Consequently, the expression level of TR4 and its target genes are reduced in liver-specific SIRT7 knockout mice and lipid synthesis and storage is decreased to resist hepatic steatosis." (PMID 30510540, 2018). "Reintroduction of SIRT7 represses ER stress and reverts fatty liver disease." (PMID 30216989, 2018).
atherosclerosis (12 papers, 2018 to 2025). A disease characterized by the build-up of fatty material and calcium deposition in the arterial wall resulting in partial or complete occlusion of the arterial lumen. "In conclusion, GLSP alleviated vascular aging and age-associated atherosclerosis and calcification by activating Sirt7." (PMID 40225574, 2025). "The intrinsic mechanism underlying the protection exerted by SIRT7 on an individual from premature endothelial senescence and atherosclerosis is yet to be explored." (PMID 34981113, 2022). "Based on the current results, future SIRT7 studies might explore the mechanism underlying endothelial homeostasis in age-related diseases, and a treatment strategy for atherosclerosis based on its rescue effect in oxide stress-induced endothelial dysfunction." (PMID 34981113, 2022). "Specifically, SIRT7 inhibited the proliferation and migration of vascular smooth muscle cells, thus offering a novel therapeutic strategy against atherosclerosis." (PMID 40884727, 2025). "In summary, these results indicated that GLSP mitigated vascular aging, atherosclerosis and vascular calcification through activating the Sirt7-Nrf2 axis." (PMID 40225574, 2025). "Mechanistically, GLSP mitigated vascular aging, atherosclerosis and vascular calcification by upregulating Sirt7 expression." (PMID 40225574, 2025). "Our study identified Sirt7 as a key modulator of Keap1 acetylation and Nrf2 activation, suggesting its therapeutic potential for vascular aging pathologies, such as atherosclerosis and vascular calcification." (PMID 40225574, 2025). "SIRT7 limits the unnecessary proliferation of VSMCs and provides protection against atherosclerosis in multiple ways." (PMID 37676263, 2024). "In summary, these studies show that SIRT7 plays a protective role against the development and progression of atherosclerosis by tightly controlling proliferation, migration, and survival of VSMCs." (PMID 37676263, 2024). "In the oxidized low-density lipoprotein (ox-LDL)-induced model of atherosclerosis, SIRT7 inhibits proliferation and migration of human VSMCs by enhancing Wnt/β-catenin signaling." (PMID 37676263, 2024). "In a similar in vitro model, miR-1306-5p aids the progression of atherosclerosis by downregulating SIRT7, thus promoting proliferation, migration, and invasion of VSMCs." (PMID 37676263, 2024). "SIRT7 inhibits the progression of atherosclerosis by decreasing the proliferation and migration of vascular smooth muscle cells." (PMID 33614337, 2021). "This study suggested that Sirt7 may be a target for treating vascular aging, and GLSP may be a new strategy for treating vascular aging, and aging-associated atherosclerosis and vascular calcification." (PMID 40225574, 2025). "In addition, SIRT7 is targeted by miR-335 to induce endothelial senescence and contributes to the pathogenesis of atherosclerosis." (PMID 37676263, 2024). "This indirectly proves the significant role of SIRT7 in atherosclerosis." (PMID 35677446, 2022). "Certain small molecules have been found to affect atherosclerosis by modulating SIRT7 expression." (PMID 35677446, 2022). "However, little is known about the role of SIRT7 in atherosclerosis." (PMID 30627559, 2018).
atherosclerosis (continued). "As an approach to counteract atherosclerosis, upregulation of the long noncoding RNA (lncRNA) SNHG7-003, which is downregulated in response to ox-LDL treatment of VSMCs, sequesters miR-1306-5p from SIRT7 transcripts, thus preventing its downregulation." (PMID 37676263, 2024). "One limitation of the present study is the lack of the data on the effect of SIRT7 and miR-335-5p on animal models of atherosclerosis or endothelial senescence." (PMID 34981113, 2022). "The link between SIRT7, histone deacetylation and VC is not clear, but certain investigations have found that SIRT7 has a protective effect on the progression of VC, especially in atherosclerosis." (PMID 35677446, 2022).
Glucose intolerance (12 papers, 2016 to 2025). Glucose intolerance (GI) can be defined as dysglycemia that comprises both prediabetes and diabetes. "Besides, Sirt7 knockout mice were resistant to glucose intolerance and insulin sensitivity is improved in Sirt7 knockout mice receiving a high-fat diet." (PMID 27916001, 2016). "However, it has been reported that Sirt7 KO mice are resistant to weight gain, fatty liver, and glucose intolerance induced by a high-fat diet, suggesting that the reduced expression of Sirt7 may have a protective effect." (PMID 34439446, 2021). "Moreover, mice lacking SIRT7 display better resistance to glucose intolerance and increased insulin sensitivity when fed fat-containing diets, which suggests that SIRT7 plays a crucial role in glucose metabolism." (PMID 36815979, 2023).
bladder cancer (10 papers, 2018 to 2024). "The siRNA-mediated SIRT7 downregulation that causes increased apoptosis, and reduced proliferation and motility of bladder cancer cells further supports the tumor promoting capacity of SIRT7 deacetylase for the disease." (PMID 30875794, 2019). "They observed that in bladder cancer, hsa-miR-125b and SIRT7 are inversely associated with the oncogenic long non-coding RNA MALAT1." (PMID 30510540, 2018). "According to the results, SIRT7 correlated with the sensitivity of bladder cancer cells to both the platinum-based chemotherapy and CDDP." (PMID 39719443, 2024). "Herein, the collaborative regulatory roles and underlying mechanisms of SIRT7 and EZH2 in CDDP resistance in bladder cancer were explored." (PMID 39719443, 2024). "A connection between SIRT7 and EMT has been demonstrated in bladder cancer, where SIRT7 silencing decreased E-cadherin expression and increased EMT markers, such as N-cadherin, Slug and Snail." (PMID 35745656, 2022). "Hsa-miR-125b can also inhibit the development of bladder cancer by inhibiting SIRT7 and MALAT1, and has additionally been found to play an essential role in the progression of oral squamous cell cancer (OSCC), as well as the target genes and transcription factors associated with hsa-miR-125b." (PMID 34315491, 2021). "Recent reports have indicated that MALAT1 directly binds to miR‐125b and regulates SIRT7 expression in bladder cancer 17; we investigated whether MALAT1 has similar inhibitory effects on miR‐125b levels in MM cells." (PMID 29214735, 2018). "On the other hand, the crucial regulatory involvement of SIRT7 and EZH2 in bladder cancer development is well known." (PMID 39719443, 2024). "Overall, in the promoter region of the RND3 gene, SIRT7 upregulated H3K27me3 and EZH2 downregulated H3K18ac, leading to a decline in RND3 expression and CDDP sensitivity in bladder cancer cells." (PMID 39719443, 2024). "Immunohistochemistry (IHC) and Western Blot (WB) analyses were used to assess the expression levels of SIRT7/EZH2 and RND3 in bladder cancer tissues, normal ureteral epithelial cells, and bladder cancer cell lines." (PMID 39719443, 2024). "Up-regulated hsa-miR-125b resulted in down-regulated SIRT7 and MALAT1; this effect inhibited bladder cancer cell growth, induced apoptosis, and decreased cell motility." (PMID 30510540, 2018). "Therefore, targeting SIRT7 and EZH2 could be a viable approach to enhancing CDDP efficacy in bladder cancer treatment." (PMID 39719443, 2024).
diabetes (10 papers, 2015 to 2026). "This evidence suggests that elevating Sirt7 levels ameliorates renal dysfunction in cases of diabetes‐induced renal injury, primarily through the inhibition of EndMT." (PMID 38686489, 2024). "Interestingly, elevated glucose concentrations similar to those seen in decompensated diabetes or during daily hyperglycaemic spikes were able to suppress SIRT7 to the same extent as did osteogenic conditions." (PMID 35708762, 2022). "Additionally, the persistent exposure of diabetic cells to high glucose concentrations (25 mM) promoted the upregulation of caveolin-1, N-cadherin, SIRT3, SIRT7 and lactate levels, suggesting that long-term diabetes may promote cell proliferation." (PMID 30093732, 2018). "Herein, we demonstrated that Sirt7 was decreased in glomeruli of DKD and MD patients and diabetes‐induced renal injury rats, as well as in HGECs cultured in HG and MM conditions." (PMID 38686489, 2024). "Lower levels of SDC1 and Sirt7 were noted in the glomeruli of both DKD patients and diabetes‐induced renal injury rats, as well as in human glomerular endothelial cells (HGECs) with high blood sugar." (PMID 38686489, 2024). "The decreased expression of Sirt7 in glomerulus of DKD participants and diabetes‐induced renal injury rats in our study confirmed it, which was preserved even after glycaemia turned to normal." (PMID 38686489, 2024). "Conversely, SIRT4 and SIRT7 exhibited negative effect on diabetes therapy, such as aggravating lipogenesis, and inhibiting insulin secretion." (PMID 30559718, 2018). "Some genes such as Sirt7, Tbk1 and Lamp2 were significantly overexpressed in the group developing diabetes after 17 weeks, but expression did not correlate with time of diabetes onset." (PMID 26366287, 2015).
pulmonary fibrosis (10 papers, 2020 to 2026). Chronic progressive interstitial lung disorder characterized by the replacement of the lung tissue by connective tissue, leading to progressive dyspnea, respiratory failure, or right heart failure. "NAMPT deficiency impaired AT2 renewal and enhanced lung fibrosis through downregulation of SIRT7 and SOD2, which resulted in increased oxidative stress, mitochondrial dysfunction, accumulated aberrant transitional cells, and impaired differentiation from AT2 to alveolar type 1 (AT1) cells." (PMID 42096291, 2026). "Finally, SIRT7 expression also decreased during pulmonary fibrosis and the overexpression of SIRT7 is associated with reduced pro-fibrotic markers." (PMID 35745656, 2022). "Besides SIRT1 and SIRT3, SIRT7 has additionally been recently proposed as a novel regulator of lung fibrosis, and directly implicated in SSc-ILD." (PMID 35268452, 2022). "This article reviews the complex molecular mechanisms of the poorly studied SIRT3, SIRT6, and SIRT7 subtypes in lung fibrosis and the latest research progress in targeting them to treat lung fibrosis." (PMID 40241794, 2025). "This article reviews the role of SIRT3, SIRT6 and SIRT7 in lung fibrosis, which are relatively understudied in the Sirtuins family." (PMID 40241794, 2025). "Studies have shown that compared with healthy control groups, the expression levels of all Sirtuins in fibroblasts from patients with pulmonary fibrosis tend to decrease, with the most significant decrease in SIRT7 expression." (PMID 40241794, 2025). "It has been confirmed that SIRT1, SIRT2, SIRT3, SIRT6 and SIRT7 significantly inhibit the development of lung fibrosis." (PMID 40241794, 2025). "SIRT7 level is decreased in a mouse model of lung fibrosis induced by bleomycin, and pharmacological inhibition of GLS1 reverses the fibrosis." (PMID 37676263, 2024). "SIRT7 was reduced the most between disease and control individuals and inhibits lung fibrosis by limiting TGF-β/SMAD3 signaling-mediated expression of alpha smooth muscle actin (α-SMA) and collagen." (PMID 37676263, 2024). "Patients with pulmonary fibrosis have been reported to display the lowest SIRT7 expression levels in fibroblasts." (PMID 37483618, 2023). "We recently showed decreased SIRT7 expression in lung tissues and fibroblasts from patients with pulmonary fibrosis compared to controls." (PMID 32719338, 2020). "In particular, the specific activation or inhibition of SIRT3, SIRT6, and SIRT7 may open up new directions for the treatment of pulmonary fibrosis." (PMID 40241794, 2025). "In summary, targeting the SIRT6-PPARα-mediated lipolysis and the TGF-β/SIRT7/FOXO4-regulated glutamine metabolic pathway may be a potential strategy for the treatment of pulmonary fibrosis and related diseases." (PMID 40241794, 2025). "Among these Sirtuins, Sirt1, Sirt3, Sirt6, and Sirt7 have been well studied in pulmonary fibrosis." (PMID 34925016, 2021). "This review focuses on the role of SIRT3, SIRT6, and SIRT7 in fibrotic diseases, analyzes their molecular regulatory mechanisms in pulmonary fibrosis, and summarizes the latest research progress for the therapy of IPF using SIRT3, SIRT6, and SIRT7 as targets." (PMID 40241794, 2025). "However, compared with cardiovascular and liver fibrosis, studies on Sirtuins in pulmonary fibrosis are still relatively rare, especially those on SIRT3, SIRT6 and SIRT7." (PMID 40241794, 2025). "SIRT7 silencing induces endothelial-to-mesenchymal transition in lung vascular endothelial cells by promoting TGF-β signaling, which compromises the endothelial barrier and increases vascular permeability and inflammatory responses, leading to lung fibrosis." (PMID 37676263, 2024).
acute kidney injury (9 papers, 2018 to 2025). Sudden and sustained deterioration of the kidney function characterized by decreased glomerular filtration rate, increased serum creatinine or oliguria. "The beneficial effects of SIRT7 deprivation have been also described in acute kidney injury, where the sirtuin deficiency ameliorated the inflammatory response related to cisplatin treatment." (PMID 38791128, 2024). "A previous study indicates that SIRT7 deficiency ameliorates DDP-induced acute kidney injury by modulating inflammatory response." (PMID 39020302, 2024). "Sirt7 directly downregulates NF-κB expression, reducing cisplatin-induced acute kidney injury and attenuating apoptosis in renal tubular epithelial cells." (PMID 39911234, 2024). "Sirt7 directly reduces NF-κB expression, attenuates cisplatin-induced acute kidney injury, and alleviates renal tubular epithelial cell apoptosis." (PMID 38347622, 2024). "Zn2+ upregulated Parkin acetylation by repressing sirtuin 7 activity to promote mitophagy and inhibit NLRP3 inflammasome activation and pyroptosis, thus improving sepsis-induced acute kidney injury." (PMID 40989844, 2025).